SPA17 (sperm autoantigenic protein 17)
Description:
Sperm surface zona pellucida binding protein. Helps to bind spermatozoa to the zona pellucida with high affinity. Might function in binding zona pellucida and carbohydrates (By similarity).
Synonyms: CT22; SP17; SP17-1
Tractability: Small molecule: a structure with a bound ligand is known. Antibody: UniProt places it where antibodies can reach, with high confidence; its Gene Ontology location is reachable by antibodies, with medium confidence. PROTAC: ubiquitination databases record sites on it.
Gene: Protein-coding gene on chromosome 11 (124,673,796 to 124,698,309, forward strand). Ensembl gene ENSG00000064199.
Subcellular location: Membrane
Subcellular location (Human Protein Atlas): Golgi apparatus; Principal piece; Vesicles
Gene Ontology:
Molecular function: protein binding; calmodulin binding
Biological process: epithelial cilium movement involved in extracellular fluid movement; single fertilization; spermatogenesis; binding of sperm to zona pellucida
Cellular component: cilium; cytoplasm; motile cilium; sperm fibrous sheath; sperm principal piece; external side of plasma membrane; extracellular region; membrane
Genetic constraint (gnomAD): Loss-of-function variants: 6 observed, 10.51 expected, observed/expected ratio (o/e) 0.57, 90% interval 0.31 to 1.13. The upper end of that interval is the gene's LOEUF score, 1.13, which puts it in group 4 of 6, group 1 being the genes least tolerant of losing a copy. Missense variants: 141 observed, 157.92 expected, observed/expected ratio (o/e) 0.89, 90% interval 0.78 to 1.03. Synonymous variants: 52 observed, 52.8 expected, observed/expected ratio (o/e) 0.98, 90% interval 0.79 to 1.24.
Homologues: Orthologues: chimpanzee SPA17 (100% identical), macaque SPA17 (97% identical), dog SPA17 (75% identical), pig SPA17 (75% identical), rat Spa17 (73% identical), mouse Spa17 (72% identical), rabbit SPA17 (61% identical), guinea pig SPA17 (60% identical), Caenorhabditis elegans F39H12.3 (26% identical), Drosophila melanogaster igl (13% identical). Paralogues in human: GAP43 (19% identical), RIIAD1 (14% identical).
Diseases named in the same sentence as SPA17 in open-access papers:
SPA17 is named in the same sentence as 30 diseases in open-access papers, as found by Europe PMC text mining. Sharing a sentence is not in itself a finding about the gene and the disease. The quoted sentences say what the papers report.
infertile (4 papers, 2019 to 2022). "Therefore, the downregulation of HSPA2, BAG6, and SPA17 in the present study indicates that sperm and oocyte recognition may be associated with the abnormal sperm linked with infertility." (PMID 34213690, 2021). "In our earlier study, we reported the underexpression of SPA17 in men with primary or secondary infertility." (PMID 31336797, 2019). "An in-depth functional analysis of sperm proteins revealed that SPA17 and fibronectin (FN1) associated with reproductive system development and function were underexpressed in normozoospermic infertile men." (PMID 31336797, 2019). "Thus, the present study, in relation to the individual previous studies, aims to identify SPA17, PPP1R36, AURKA, TRIP13, PLK4, CCDC90B, and CCDC91 genes as important biomarkers of both teratozoospermia- and azoospermia-associated infertility in men." (PMID 36292606, 2022). "Whereas, increase in the expression of SPA17 in these same patients following antioxidant treatment indicates the role of antioxidants in the restoration of physiological spermatogenesis in idiopathic infertile men." (PMID 31623114, 2019). "Therefore, underexpression of SPA17 may affect sperm capacitation and sperm–oocyte binding in normozoospermic infertile patients." (PMID 31336797, 2019). "Of the four validated proteins, SPA17 and SERPINA5 were underexpressed and ANXA2 was overexpressed (p < 0.05) in UMI subjects, whereas the expression level of PRDX2 was comparable for normozoospermic fertile and infertile men." (PMID 31336797, 2019).
ovarian carcinoma (3 papers, 2019 to 2023). A malignant neoplasm originating from the surface ovarian epithelium. "In direct alignment with our results, previous studies have shown that overexpression of SPA17 leads to increased chemoresistance in ovarian cancer cell, while knockdown of SPA17 increased chemosensitivity." (PMID 37533202, 2023). "As a type of CTA, recent studies have also found SPA17 expression in various tumors, including ovarian cancer, breast cancer, multiple myeloma, cervical cancer, endometrial cancer, and non-small cell lung cancer." (PMID 35592314, 2022). "Previous studies also underline the potential cancer immunogenicity and immunotherapy targeting the role of the SPA17 protein or transcript in various cancers, such as ovarian cancer, esophageal squamous cell carcinoma, and multiple myeloma." (PMID 35592314, 2022). "Another study on ovarian cancer showed that SPA17 could be used as a new biomarker for OC immunotherapy." (PMID 35592314, 2022).
varicocele (3 papers, 2015 to 2024). A condition characterized by the dilated tortuous veins of the spermatic cord with a marked left-sided predominance. "A study of varicocele sperm shows that a low SPA17 expression of SPA17 was related to mitochondrial damage, which is also crucial for the intracellular homeostasis of cancer cells and the cancer therapy effect." (PMID 35592314, 2022). "We found that sperm surface protein SPA17 was underexpressed with very low abundance in the unilateral varicocele group." (PMID 25890347, 2015). "Notable proteins include calcium-binding tyrosine phosphorylation-regulated protein (CABYR), A-kinase anchor proteins (AKAP), APOA1, semenogelin-1 (SEMG1), and sperm surface protein Sp17 (SPA17), which have been highlighted as potential biomarkers for unilateral varicocele." (PMID 39685846, 2024). "CABYR, SEMG-1 preproprotein, RSPH1and SPA17 were underexpressed in the unilateral varicocele group." (PMID 25890347, 2015).
breast carcinoma (2 papers, 2019 to 2025). "All of our results indicated that SPA17 plays a vital role in the development, migration, and invasion of breast cancer and that it can be used as an important diagnostic and prognostic indicator in clinical practice." (PMID 31417875, 2019). "SPA17, as another important finding in this study, has been identified as a predictor of poor clinical outcomes in malignancies such as breast cancer and as an effective immunotherapy response predictor in tumor patients." (PMID 40165483, 2025). "In this study, we systematically studied the expression of SPA17 in breast cancer tissues and its function in the development of breast cancer." (PMID 31417875, 2019). "Whatever, these studies have confirmed that SPA17 expressed in breast cancer, and its expression had a relationship with molecular subtyping." (PMID 31417875, 2019). "With further analysis, we also observed that the expression of SPA17 was higher in patients with lymph node metastasis (55.6%), Cox regression analysis showed SPA17 was an independent factor associated with DFS and OS in breast cancer patients." (PMID 31417875, 2019). "The lowest and the highest expression of SPA17 were found in Luminal A and triple-negative subtype breast cancer, respectively." (PMID 31417875, 2019). "We observed that the positive expression rate of SPA17 was higher in patients with lymph node metastasis, indicating that SPA17 expression likely promoted lymph node metastasis in breast cancer." (PMID 31417875, 2019). "We examined the expression of SPA17 in breast cancer and assessed its effect on patient prognosis and its function in breast cancer development." (PMID 31417875, 2019). "The expression of SPA17 mRNA and protein were further determined in 100 breast cancer specimens and 20 normal breast tissues by quantitative real-time PCR and immunohistochemistry." (PMID 31417875, 2019). "If so, we finally focus on the mechanisms by which SPA17 affects the prognosis of breast cancer through cytological studies." (PMID 31417875, 2019). "In terms of SPA17 protein positive expression rate in breast cancer tissues, our rate was relatively high, which up to 27%." (PMID 31417875, 2019). "All of these results provided strong support for us to further explore the function of SPA17 in breast cancer." (PMID 31417875, 2019). "We found that SPA17 was expressed at the mRNA and protein levels only in breast cancer specimens, especially in triple-negative (60%) or HER2-positive (45%) subtypes, and not in normal breast tissues." (PMID 31417875, 2019). "A previous study conducted by Gjerstorff and Ditzel reported the overall expression of SPA17 to be 12% in breast cancer patients they reviewed, which is lower than what we observed in our study." (PMID 31417875, 2019). "Whether SPA17 can be used as a prognostic marker for breast cancer will require a study of a larger sample size." (PMID 31417875, 2019). "Considering the lowest expression and the highest expression of SPA17 in Luminal A breast cancer and triple-negative breast cancer, respectively, we selected MCF-7 and MDA-MB-231 cells to verify the role of SPA17 in regulating the biological function of breast cancer cells." (PMID 31417875, 2019). "Combined with relevant immunological research and mechanism exploration, SPA17 may be a new therapeutic target to improve the prognosis of breast cancer, especially the triple-negative and HER2-positive subtypes, in the future." (PMID 31417875, 2019). "We found that the expression of SPA17 may be related to the metastasis of breast cancer." (PMID 31417875, 2019). "The results showed SPA17 protein was expressed in 27% (27/100) of breast cancer specimens and in none of the normal breast samples." (PMID 31417875, 2019). "Besides, the expression of SPA17 was also related to molecular subtyping, it expressed more in triple-negative (60%) or HER2 positive (45%) breast cancers." (PMID 31417875, 2019).
breast carcinoma (continued). "The expression of SPA17 mRNA in breast cancer specimens was similar to that of SPA17 protein, but not expressed in normal breast samples." (PMID 31417875, 2019). "SPA17 mRNA and protein expression were positive in the majority of non-luminal breast cancer samples." (PMID 31417875, 2019). "Our result also showed that 27% (27/100) of breast cancer samples expressed SPA17 but none of the normal breast (0/20) samples did." (PMID 31417875, 2019). "Previously, it was found that MCF-7 cells did not express SPA17, and their migration and invasion abilities were relatively weak compared to those of the other three subtypes of breast cancer cells." (PMID 31417875, 2019). "Therefore, we selected the MCF-7 and the MDA-MB-231 cell line for functional verification of SPA17 overexpression and silencing, and Q-PCR and western blot confirmed that MCF-7 breast cancer cells hardly expressed SPA17, while MDA-MB-231 breast cancer cells highly expressed SPA17." (PMID 31417875, 2019). "In addition, cell function assay validated that SPA17 increased the migration (p < 0.001) and invasion (p = 0.007) of breast cancer cells, but not affected the proliferation of breast cancer cells." (PMID 31417875, 2019). "Previously, whether the expression of SPA17 is related to breast cancer prognosis has not yet been reported." (PMID 31417875, 2019). "Since SPA17 expression was more frequently observed in samples from patients with lymph node metastasis of breast cancer and the triple negative and HER2 positive breast cancer specimens, we supposed that SPA17 expression might affect the prognosis of breast cancer patients." (PMID 31417875, 2019). "We performed the MTT assay showed that SPA17 overexpression did not increased the proliferation of MCF-7, while SPA17 depletion inhibited the proliferation rate of MDA-MB-231 breast cancer cells slightly, but the differences were not statistically significant (p > 0.05)." (PMID 31417875, 2019).
Azoospermia (1 paper, 2022). Absence of any measurable level of sperm,whereby spermatozoa cannot be observed even after centrifugation of the semen pellet. "Hence, SPA17 is negatively expressed in teratozoospermia or azoospermia as it remained down-regulated in the disease conditions as compared to the control." (PMID 36292606, 2022).
cervical cancer (1 paper, 2012). A primary or metastatic malignant neoplasm involving the cervix. "Increased expression of spa17 has been detected in esophageal, ovarian, and cervical cancers and has been used as a clinical marker for cancer in these tissues." (PMID 22438865, 2012).
glioblastoma (1 paper, 2022). The most malignant astrocytic tumor (WHO grade IV). "We performed a western blotting assay to validate the upregulated SPA17 expression in clinical glioblastoma (GBM) samples." (PMID 35592314, 2022). "This study used transcriptomic data of the TCGA-Pan-cancer cohort and GTEx dataset to reveal the SPA17 expression difference between normal human and tumor tissues, and a western blot was performed to detect the upregulated expression of SPA17 in clinical glioblastoma (GBM) samples." (PMID 35592314, 2022).
invasive breast carcinoma (1 paper, 2019). A carcinoma that infiltrates the breast parenchyma. "Moreover, we reviewed the Oncomine database and found that in the Curtis and The Cancer Genome Atlas datasets, the expression of SPA17 in invasive breast carcinoma was higher than that in normal breast, and the difference was statistically significant." (PMID 31417875, 2019).
lymph node metastasis (1 paper, 2019). "Our analyses further revealed that the expression of SPA17 was associated with lymph node metastasis (p < 0.001), ER status (p < 0.001), PR status (p = 0.003), molecular subtyping (p < 0.001), Endocrine-therapy (p < 0.001) and Radiotherapy (p < 0.001)." (PMID 31417875, 2019). "Lymph node metastasis (p < 0.001) and molecular subtyping (p = 0.002) were independent factors associated with SPA17 expression." (PMID 31417875, 2019). "While SPA17, lymph node metastasis, tumor size, PR status, Ki-67 status, molecular subtyping, endocrine-therapy and radiotherapy were associated with disease-free survival." (PMID 31417875, 2019). "Further analysis revealed that 61.8% (21/34) of patients with lymph node metastasis had positive SPA17 expression." (PMID 31417875, 2019). "As a potential prognostic and theraputic target, we did the Cox regression univariate analysis, the results showed SPA17, lymph node metastasis, tumor size, ER status, PR status, molecular subtyping, endocrine-therapy and radiotherapy were associated with overall survival." (PMID 31417875, 2019). "In this study, we analyzed the status of SPA17 expression and lymph node metastasis in patients." (PMID 31417875, 2019). "About 77.8% (21/27) of patients with SPA17 expression had lymph node metastasis." (PMID 31417875, 2019).
lymphoid tumors (1 paper, 2014). "We have previously reported on the activation of neuronal neurogranin (Nrgn) in T-cell lymphomas induced by SL3-3 integration in the Esam/Vsig2/Nrgn/Siae/Spa17 locus where the Nrgn expression level in lymphoid tumors corresponded to brain levels." (PMID 24886479, 2014).
melanoma (1 paper, 2022). A malignant, usually aggressive tumor composed of atypical, neoplastic melanocytes. "In the GSE91061 melanoma cohort, melanoma patients with low SPA17 expression had a better chance of survival than patients with high SPA17 expression." (PMID 35592314, 2022). "We next explored the relationship between SPA17 expression levels and the response to anti-PD-L1 immunotherapy in a pan-cancer cohort, including kidney renal clear cell carcinoma and the expression levels of anti-PD1 in melanoma." (PMID 35592314, 2022).
multiple myeloma (1 paper, 2022). "have shown that SPA17 was a new CTA of multiple myeloma (MM) and a suitable target for its tumor vaccine." (PMID 35592314, 2022).
pancreatic cancer (1 paper, 2023). "Increased levels of SPA17 and CD58 were previously linked to poor prognostic outcome in breast and pancreatic cancer patients, respectively." (PMID 37533202, 2023).
pulmonary fibrosis (1 paper, 2025). Chronic progressive interstitial lung disorder characterized by the replacement of the lung tissue by connective tissue, leading to progressive dyspnea, respiratory failure, or right heart failure. "Additionally, linear regression data demonstrated that SPA17 expression was negatively correlated with FVC‐pre, FVC‐pro, and DLCO, suggesting that elevated SPA17 levels may be linked to worse clinical outcomes in pulmonary fibrosis patients." (PMID 40165483, 2025). "To further explore the potential relationship between SPA17 and clinical outcomes in pulmonary fibrosis patients, we downloaded data from GSE47460 (lung tissues from 254 IPF patients and 108 healthy controls) and GSE150910 (lung tissues from 103 IPF patients and 103 healthy controls)." (PMID 40165483, 2025).
sarcoma (1 paper, 2024). A usually aggressive malignant neoplasm of the soft tissue or bone. "We performed immunohistochemistry (IHC) on DDLS and WDLS to confirm protein expression of TTK, PBK and SPA17, as well as CTAs commonly expressed in sarcoma including NY-ESO-1 (included in Nanostring panel as CTAG1B), SSX2 and MAGE-A3, some of which that have been targeted by adoptive cell therapy." (PMID 38755218, 2024).
systemic lupus erythematosus (1 paper, 2005). An autoimmune multi-organ disease typically associated with vasculopathy and autoantibody production. "The exceptions to this are humoral immune responses to MAGEB1/CT3.1 in systemic lupus erythematosus patients and to SPA17/CT22 in vasectomised men." (PMID 15715909, 2005).
testicular germ cell tumor (1 paper, 2022). A germ cell tumor arising from the testis. "The highest SPA17 alteration frequency (>6%) appeared for patients with testicular germ cell tumors (TGCT) with “Deep Deletion” as the primary type." (PMID 35592314, 2022).
thymic carcinoma (1 paper, 2022). Thymic carcinoma (TC) is a type of thymic epithelial neoplasm characterized by a high malignant potential. "Likewise, we found SPA17 was significantly correlated with multiple infiltrating immune cells, such as macrophages, B cells, CAF, and CD8+ T cells, in thymic carcinoma (THYM) and thyroid carcinoma (THCA)." (PMID 35592314, 2022).
urinary system tumors (1 paper, 2022). "In the urinary system tumors of the IMvigor210 cohort, the anti-PD-L1 response rate of patients with high SPA17 expression was 32.08%, which was significantly higher than 20.82% of patients with low SPA17 expression." (PMID 35592314, 2022).